MAP2K1 (mitogen-activated protein kinase kinase 1)
Diseases named in the same sentence as MAP2K1 in open-access papers (continued):
Sharing a sentence is not in itself a finding about the gene and the disease.
melanoma (continued). "In the STE group (which includes MAP kinases), column 269 was identified; this position contains numerous recurrent mutations in the group, including P124S in MAP2K1 which is common in melanomas." (PMID 28743916, 2017). "MAP2K1 has been identified as an occasional driver in non-small cell lung cancer, and sustained gain-of-function mutations in melanoma." (PMID 28333948, 2017). "Screening of a larger cohort of melanoma tumors revealed the presence of recurring somatic MAP2K1 and MAP2K2 mutations at an overall frequency of 8%." (PMID 24743024, 2014). "Sequencing of seven melanoma cell lines and donor-matched germline cells found MAP2K1 and MAP2K2 (MEK1 and MEK2, respectively) mutations, resulting in constitutive ERK phosphorylation and higher resistance to MEK inhibitors." (PMID 24743024, 2014). "Interestingly, the gene expression levels of CD33, a marker of myeloid-derived suppressor cells (MDSCs), and IL-10, which is mainly secreted by regulatory T cells (Tregs), were higher in MAP2K1/2-mutated melanoma, compared to those in wild-type melanoma." (PMID 35069558, 2021). "These processes might account for the superiority of anti-CTLA-4 therapy over anti-PD-1 therapy in MAP2K1/2-mutated melanomas." (PMID 35069558, 2021). "To further identify more novel predictive biomarkers, we performed data analysis using several public cohorts and found that MAP2K1/2 mutations might be a potential predictor for the clinical benefits of anti-CTLA-4 therapy in advanced melanomas." (PMID 35069558, 2021). "The influence of MAP2K1/2 mutations on the expression of immunity-related genes was also evaluated by analysing the RNA expression profile data collected from these cohorts and from the Cancer Genome Atlas (TCGA) melanoma cohort." (PMID 35069558, 2021). "With an innovation-based view, we suggest that for patients with MAP2K1/2-mutated melanoma, anti-CTLA-4 therapy might be more effective than anti-PD-1 monotherapy." (PMID 35069558, 2021). "Moreover, MDSCs and Tregs were reported to be associated with resistance to the PD-1 blockade, consistent with the poor prognosis of patients with MAP2K1/2-mutated melanoma who received anti-PD-1 therapy." (PMID 35069558, 2021). "In addition, we observed an increase in B cells, CD8+ T cells, and neutrophils in MAP2K1/2-mutated melanomas, as compared to MAP2K1/2-wild-type melanomas." (PMID 35069558, 2021). "Nevertheless, the influence of previous targeted therapies on the therapeutic effect of immunotherapy in MAP2K1/2-mutated melanoma is unknown." (PMID 35069558, 2021). "Due to the lack of available data, we could not compare the differences in the efficacy of anti-CTLA-4 monotherapy and combination therapy involving both anti-CTLA-4 anti-PD-1 in patients with MAP2K1/2-mutated melanoma in this study." (PMID 35069558, 2021). "The results suggested that MAP2K1/2 mutations might be an independent predictor for a favourable clinical response to anti-CTLA4 therapy in patients with melanoma." (PMID 35069558, 2021). "Anti-CTLA-4 treatment might be more effective than anti-PD-1 therapy for patients with MAP2K1/2-mutated melanoma." (PMID 35069558, 2021). "Activating mutations in MAP2K1 have been identified in melanoma." (PMID 33040161, 2021).
melanoma (continued). "A single case of stage IV melanoma of unknown primary was identified to have an in-frame deletion in MAP2K1 (E102_103del) at allele frequency (AF) of 3.85%." (PMID 32483240, 2020). "Additional studies on therapeutic approaches to MAP2K1-mutated melanomas are needed." (PMID 32483240, 2020). "Moreover, the coexistence of mutated BRAF and gain-of-function MAP2K1/MAP2K2 mutations was detected in two melanomas and resulted in higher resistance to MEK inhibitors." (PMID 32847629, 2020). "While prior in vitro and clinical studies have correlated MAP2K1 missense mutations with resistance to targeted inhibitors in the context of BRAF-mutated melanomas, targeted therapy for melanoma with MAP2K1 in-frame deletion has not been reported to our knowledge." (PMID 32483240, 2020). "Additionally, the number of MDSCs and Tregs is increased in MAP2K1/2-mutated melanomas." (PMID 35069558, 2021). "Trametinib, a highly specific MAP2K1/2 inhibitor approved by the FDA for the treatment of tumors such as melanoma and non-small cell lung cancer, was used as the MEKi in this experiment." (PMID 39781472, 2025). "During a median follow-up of 32 months (IQR 15–46 months), 15 melanoma patients (28.8%), all with pT2a–pT4b tumours, developed metastatic melanoma: nine with Class I, three with Class II, and three with Class III MAP2K1 mutations." (PMID 40107205, 2025). "Among the 50 patients in the non-melanoma group, two had MAP2K1-driven tumours originating from a medium-sized congenital nevus and a nevus spilus." (PMID 40107205, 2025). "Class I MAP2K1 mutations, which were consistently accompanied by co-driver MAPK pathway mutations, were almost exclusively found in melanomas and were strongly associated with metastatic disease." (PMID 40107205, 2025). "A375 melanoma cells show isoform dependency on MAPK1/MAP2K1, also observed in DepMap screens in BRAF-driven melanoma cells." (PMID 38678031, 2024). "The OFA has been specifically designed to provide comprehensive genomic profiling of solid tumors and includes the mutational study of melanoma-related genes such as BRAF, NRAS, KIT, MAP2K1, or HRAS." (PMID 39000050, 2024). "In the mouse melanoma model, Map2k1 and Prkacb mRNA levels exhibited a progressive increase with tumor progression, supporting their role in melanoma advancement." (PMID 39835132, 2024). "This is the first published case of a durable intracranial disease control with the MEK-inhibitor trametinib of a stage IV-M1d class-2 MAP2K1-mutant melanoma." (PMID 39314226, 2024). "This study provides an integrated approach to understanding the AhR pathway’s role in melanoma, identifying MAP2K1, PRKACB, KLF5, and PIK3R2 as critical prognostic markers and therapeutic targets." (PMID 39835132, 2024). "In MAP2K1-mutant melanoma, there is one case report of a partial response to trametinib in a patient with stage IV-M1c melanoma, but resistance developed 3 months later and dose reduction was needed because of trametinib-induced skin-toxicity." (PMID 39314226, 2024). "This study presents a comprehensive analysis of AhR-related genes in melanoma, highlighting MAP2K1, PRKACB, KLF5, and PIK3R2 as key prognostic markers and potential therapeutic targets." (PMID 39835132, 2024). "We report the first case of durable intra- and extracranial response to trametinib, following local control with SRS of intracranial oligo-progression, in a patient with stage IV-M1d class-2 MAP2K1-mutant melanoma." (PMID 39314226, 2024).
melanoma (continued). "In view of the fact that the OFA includes some relevant genes in melanoma pathways apart from BRAF, such as NRAS, KIT, or MAP2K1, we embraced this panel to prospectively study a series of advanced melanoma patients." (PMID 39000050, 2024). "We present a patient with a class-2 MAP2K1-mutant stage IV-M1d melanoma who experienced extra- and intracranial progressive disease following treatment with immune-checkpoint inhibitors." (PMID 39314226, 2024). "There have been several studies that have investigated the role of somatic mutations in MAP2K1 and MAP2K2, and in MAP3K5 and MAP3K9 in melanoma." (PMID 37504268, 2023). "A number of melanoma recurrent mutations have been reported in the literature in several genes including KIT, TERT, MAP2K1 and MAP2K2, RAC and PPP6C." (PMID 36765773, 2023). "Trametinib (brand name Mekinist) is an orally bioavailable drug used to treat melanoma by the inhibition of dual specificity mitogen-activated protein kinase kinase 1 (MEK1) and MEK2." (PMID 37998343, 2023). "The custom melanoma panel detected only 50% of these four cases (based on detection of a TERT C250T mutation and a MAP2K1 H119Y mutation respectively)." (PMID 35494035, 2022). "Kinases were applicated to the clinic strategy, such as anti-EGFR (abemaciclib) in breast cancer, and anti-MAP2K1 (trametinib) in melanoma." (PMID 35397555, 2022). "Among down-regulated genes, the analysis showed several experimentally validated target genes, such as E2F7, MAP2K1 (also known as MEK1), CCNG1, HMGB2, SIRT1, belonging to key signaling pathways frequently associated to melanoma." (PMID 33670365, 2021). "When metformin was combined with the MAP2K1/2 inhibitor binimetinib, the combination treatment showed a synergistic effect in reducing melanoma colony formation and the growth of tumor spheroids." (PMID 34831420, 2021). "In another report, CRISPR RNA-guided deaminase technology was combined with CROP-seq (CRISPR droplet sequencing) technology to introduce mutations in 3 genes of the MAPK pathway in A375 melanoma cells, namely NRAS, KRAS and MAP2K1 (MEK1)." (PMID 33535416, 2021). "Moreover, except for immunity-related genes, a total of 55 significantly differentially expressed genes were found between MAP2K1/2-mutated and wild-type melanoma in clinical cohort, which might be associated with reshape of immunological microenvironment caused by MAPK mutation." (PMID 35069558, 2021). "Here, we investigated melanomas with in-frame deletions of MAP2K1, alterations characterized as MAPK-activating in recent experimental models." (PMID 32483240, 2020). "In fibroblasts, the expression of mitogen-activated protein kinase kinase 1 (MAPKK1) is strongly induced by melanoma cells secretome." (PMID 33212834, 2020). "Primary MAP2K1 and MAPK1 mutations are found in only 5.38% and 1.77% of melanoma cases, respectively, and are often inclusion criteria for patients in clinical trials with MEK inhibitors (MEKi)." (PMID 32605090, 2020). "Our case archive of clinical melanoma samples with comprehensive genomic profiling by a hybrid capture-based DNA sequencing platform was searched for MAP2K1 genetic alterations." (PMID 32483240, 2020). "Nevertheless, three lines of evidence support our inference that the in-frame deletions of MAP2K1 in our melanoma cases were activating." (PMID 32483240, 2020). "A recent study reported mutation of MAP2K1, a downstream effector of the RAS-RAF-MEK pathway, in melanoma with an overall frequency of 8%." (PMID 32847629, 2020). "To highlight the utility of our platform, we generated substitution mutations in each exon of three human genes (MAP2K1, KRAS, NRAS) associated with resistance to vemurafenib, which is a cancer drug targeting the BRAF V600E mutation in melanoma patients." (PMID 32242071, 2020). "Second is evidence of MAPK pathway activation in prior study of non-melanoma tumors with these same MAP2K1 in-frame deletions." (PMID 32483240, 2020).
melanoma (continued). "Our study also provides a proof of concept that liquid biopsy can detect ctDNA of in-frame deletion of MAP2K1 in melanoma, with a single case showing this alteration." (PMID 32483240, 2020). "Beyond melanoma, MAP2K1 deletions have been reported rarely among pigmented epithelioid melanocytoma (PEM), deep penetrating nevi (DPN), and Spitz tumors, while various MAP2K1 alterations have been identified in a range of non-melanocytic neoplasms." (PMID 32483240, 2020). "Common resistance mutations in melanoma are BRAF splice variants, BRAF amplification, neuroblastoma RAS viral oncogene homolog (NRAS) mutations and mitogen-activated protein kinase kinase 1/2 (MEK1/2) mutations." (PMID 33003483, 2020). "Their therapeutic options are further limited because BRAF-wild-type melanomas frequently display treatment resistance due to activated MEK1 (MAP2K1), PKCα, PDGFR-β, AKT, or TNFα pathways." (PMID 31615091, 2019). "For example, patient MM475 had multiple recognized melanoma driver mutations including BRAF p.V600R, RAC1 p.P29S, MAP2K1 p.P124S, TERT C228T, and DPH3 C8T." (PMID 30312528, 2019). "Activating mutations in the MAP2K1 (MEK1) oncogene and loss of the tumor suppressor gene neurofibromin 1 (NF1) are other frequent alterations in melanomas that activate the MAPK pathway, with frequencies of ~6% and ~13%, respectively." (PMID 31581557, 2019). "Recently developed targeted treatment directed against mutant BRAF and downstream mitogen-activated protein kinase (MAPK) MAP2K1 (also termed MEK1) have improved overall survival of melanoma patients." (PMID 30987166, 2019). "Four of the melanomas had BRAFV600E mutations, three had NRAS mutations, three had NF1 mutations and one had a MAP2K1 (MEK1) mutation." (PMID 27545456, 2016). "The FDA-approved anti-melanoma drug combination of trametinib and dabrafenib is evidenced here by the recognized relationship between the MAP2K1 and BRAF proteins in the MAPK signaling pathway and phosphorylation of its constituent proteins in melanoma tumors." (PMID 26262134, 2015). "Mutations in BRAF, GNA11, GNAQ, KIT, MEK1 (MAP2K1), and NRAS can be found in approximately 70% of all melanomas." (PMID 26101870, 2015). "Class I MAP2K1 mutations typically occur alongside other MAPK pathway mutations and may contribute to aggressive melanoma behaviour." (PMID 40107205, 2025). ",15, 16, 17 Our study shows that both Class II and III MAP2K1 mutations can serve as primary drivers in nevi, melanocytomas, and melanomas in the absence of co-drivers in the MAPK pathway." (PMID 40107205, 2025). "MAP2K1 encodes a mitogen-activated protein kinase (MAPK), which exhibits activating mutations implicated in several cancers including ovarian, melanoma, and lung cancers, and its inhibition has demonstrated efficacy in restraining tumor growth in these contexts." (PMID 40953111, 2025). "Beyond melanoma, Class II and III MAP2K1 mutations have been identified in spitzoid, WNT-activated, protein kinase-activated, and BAP1-inactivated tumours, but reports of MAP2K1-driven melanocytic neoplasms without additional molecular alterations are scarce, with limited clinical follow-up." (PMID 40107205, 2025). "In this report, we present in more detail the case of a patient with a triple wild-type, class-2 MAP2K1-mutant AJCC stage IV-M1d melanoma, treated in the TraMel-WT trial, who had a deep and durable response to MEK-inhibitor treatment with excellent treatment tolerance." (PMID 39314226, 2024). "In some patients, we could also exclusively detect mutations in melanoma driver genes (BRAF, NRAS, MAP2K1, KIT) suggesting that CTC analysis could complement ctDNA analysis for relevant clinical implications in personalized medicine in oncology." (PMID 38898234, 2024).
melanoma (continued). "Patients with triple wild-type melanoma may carry other oncogenic driver mutations (e.g., KIT, MAP2K1), which mostly cause direct or indirect activation of the MAPK-pathway." (PMID 39314226, 2024). "While targeted therapies against B-Raf proto-oncogene (BRAFV600) and its downstream target mitogen-activated protein kinase kinase 1/2 (MEK1/2) are beneficial for patients with BRAF mutant unresectable melanoma, acquired resistance remains a fundamental clinical challenge." (PMID 37835493, 2023). "Here we report the case of a patient with TWT melanoma with a bona fide MAP2K1 mutation without any BRAF mutations." (PMID 36901951, 2023). "In addition, amplifications at EGFR, BRAF V600E, NRAS and KRAS loci, mutations of NRAS, KRAS and MAP2K1, and PTEN loss are often observed in resistant lesions of melanoma and CRC patients with treatment of combined RAF targeted therapies 85-87." (PMID 35966590, 2022). "Moreover, the encoding genes MAP2K1 and MAP2K2 (MAP2K1/2) are frequently mutated in melanoma, with a frequency of approximately 8% of cases." (PMID 35069558, 2021). "Additionally, mutations were common in melanoma, including BRAF (50%), NRAS (30%), MAP2K1 (6%), and KIT (2.6%)." (PMID 33133157, 2020). "Most of the melanomas with MAP2K1 in-frame deletion in our study, with the exception of 6 cases with Q58_E62del, involve the kinase domain locus corresponding to Class 3 (RAF independent) MAP2K1 mutations." (PMID 32483240, 2020). "Other genomic alterations of MAP2K1 were rare in the internal series of melanomas." (PMID 32483240, 2020). "There are a series of mechanisms described that underlie the secondary resistance of BRAF-mutant melanomas that occur after BRAF inhibitor treatment, including NRAS mutations, aberrant BRAF splicing, BRAF amplifications, MAP2K1 (MEK1) mutations, PTEN and PIK3CA mutations, and COT1 overexpression." (PMID 27903987, 2017). "Notably, melanoma patients in GSE65904 with high MAP2K1 expression exhibited better outcomes." (PMID 39835132, 2024). "The results so far suggest that some mutations in the MAP2K1 and MAP2K2 genes may contribute to the primary resistance of melanoma cells to targeted therapy and should be further investigated both functionally and in clinics as a part of the genetic predictive panel." (PMID 35565444, 2022). "Taken together, these results suggested that MAP2K1/2 gene mutations are a predictor for a favourable clinical response to anti-CTLA-4 therapy in metastatic melanoma rather than a prognostic factor for melanoma." (PMID 35069558, 2021). "An examination of the expression profiles of melanoma patients from the TCGA database, compared to normal controls from the GTEx database, revealed that AHR, MAP2K1, and PRKACB were upregulated in melanoma, whereas KLF5 and PIK3R2 were downregulated." (PMID 39835132, 2024). "These analyses aim to uncover potential therapeutic strategies for melanoma by targeting key molecules in the AHR, MAP2K1, KLF5, PRKACB, and PIK3R2 signaling pathways." (PMID 39835132, 2024). "These analyses aim to identify therapeutic strategies for melanoma by targeting key genes (AHR, MAP2K1, KLF5, PRKACB, PIK3R2) and their regulatory RNA networks, offering potential for personalized treatments and novel biomarkers to improve clinical outcomes." (PMID 39835132, 2024). "Our analysis identified a robust prognostic model, with four AhR-related genes (MAP2K1, PRKACB, KLF5, and PIK3R2) emerging as key contributors to melanoma progression." (PMID 39835132, 2024). "The upregulation of AHR, MAP2K1, and PRKACB, alongside the downregulation of KLF5 and PIK3R2, suggests that these genes play critical roles in melanoma progression through various signaling pathways." (PMID 39835132, 2024).